IL1RN (interleukin 1 receptor antagonist)
Diseases named in the same sentence as IL1RN in open-access papers (continued):
Sharing a sentence is not in itself a finding about the gene and the disease.
periodontitis (13 papers, 2010 to 2024). An acute or chronic inflammatory process that affects the tissues that surround and support the teeth. "Some polymorphisms of the IL-1 gene have been studied in association with both aggressive and chronic periodontitis: IL-1α − 889, + 4845; IL-1β − 511, − 31, + 3954 and IL1RN VNTR (variable number of tandem repeats), + 2018." (PMID 30755190, 2019). "In both types of periodontitis, IL-1RN polymorphism was significantly associated with a reduced load of P. intermedia, P. gingivalis, and T. forsythia, while IL-1A polymorphism was significantly associated with an increased P. intermedia load." (PMID 29023524, 2017). "When the polymorphism of the IL-1RN gene was also present, it exerted a protective effect against periodontitis, with a reduction in the OR from 8.11 to 5.91." (PMID 29023524, 2017). "The polymorphism of the IL-1RN gene most widely studied in association with periodontitis is the variable number tandem repeat (VNTR), a penta-allelic 86-bp polymorphism (rs2234663)." (PMID 29023524, 2017). "In combination with IL1A -889 and IL1B +3954, the IL1RN R-allele was reported to have a relationship with periodontitis susceptibility." (PMID 20339487, 2010). "There are few studies investigating IL1RN gene polymorphisms in periodontitis." (PMID 30755190, 2019). "CXCL1, CXCL3, CXCL8, CSF3, IL1A, IL1B, and IL1RN all increased in JKs in periodontitis as predicted by our atlas/DEG analyses; alternatively, SKs were relatively less active compared to JKs." (PMID 38876998, 2024). "A number of retrospective studies demonstrated a correlation between polymorphisms of interleukins IL-1a, IL-1b, IL-1RN, IL-6, IL-10 as well as TNF-a and the incidence of periodontitis and peri-implant disease." (PMID 35819566, 2022). "Comparing the Average global expression profile of neutrophils from healthy PDL versus neutrophils from PDL with periodontitis revealed increased expression of genes such as Il1b, Il1rn, Cebpb, Colec12, Ptgs2, Zfp36, Egr1, Atf3, Csf1, and Lars2 in periodontitis." (PMID 39588378, 2024). "Interestingly, increased bone loss due to enhanced osteoclast formation has been noticed in Il1rn−/− mice after the induction of periodontitis as well as in rheumatoid arthritis." (PMID 32471111, 2020). "Within genotyping to reveal an increased risk of immune reactivity associated with rapid progression of periodontitis, patients H1, H2, H3, H8, H9 and H10 were found to have a positive genotype within the polymorphism in the genes IL1-A (rs1800587), IL1-B (rs1143634) and IL-1RN (rs419598)." (PMID 36290432, 2022). "However, the contribution of IL-1RN gene and gene combinations to susceptibility to periodontitis has not been fully elucidated." (PMID 29023524, 2017).
Sepsis (12 papers, 2014 to 2025). Sepsis is defined as life-threatening organ dysfunction caused by a dysregulated host response to infection. "While we didn’t find any variants of IL1RN or CD14 to be associated with sepsis, we found two variants of tissue factor pathway inhibitor (TFPI), an anticoagulant protein, to be associated with Sepsis-2, but not Sepsis-3." (PMID 35275946, 2022). "As expected, the model demonstrated a direct relationship between norepinephrine and lactic acid, but also identified upregulated IL1RN from the mRNAseq dataset as directly involved with sepsis-associated hypotension." (PMID 34573990, 2021). "The IL1RN*2 allele has been associated with an increase in the susceptibility to sepsis and clinically severe sepsis in adults, but also to an increased risk of septic shock in children with ALL." (PMID 33339376, 2020). "Consistent with the observation of the increase in CXCR2+ and CD274+IL1RN+ neutrophil subpopulations in sepsis, the amplification of CXCR2+ and PD‐L1+ subpopulations was observed in both blood and BALF neutrophils in immunosuppressive sepsis patients." (PMID 39887584, 2025). "AE prominently downregulated CXCL-1, CXCL-8, IL-6, TNF-α, Glu1, and HMGB1 mRNA expression but activated IL-1RN, IL-10, Sirt-1, and Nrf-2 mRNA expression in the lung during sepsis." (PMID 34493741, 2021). "Specifically, following sepsis, F4/80hi macrophages polarize toward an anti-inflammatory phenotype and exhibit elevated expression of anti-inflammatory genes such as Socs3, Il1r2, and Il1rn." (PMID 41465886, 2025). "Together with the results from CLP sepsis mice, we considered CD274+IL1RN+ mature neutrophils to be immunosuppressive effector cells in the lung environment during sepsis‐induced immunosuppression, which can transition from intermediate‐state CXCR2+ neutrophils." (PMID 39887584, 2025). "Upregulation of IL1RN protein levels was described in patients with sepsis and septic shock." (PMID 34573990, 2021). "IL1RN was also tested in an unsuccessful clinical trial as a therapeutic agent for sepsis." (PMID 34573990, 2021). "Previous prospective trials of inhibitors or antibodies to gene products linked to sepsis, such as IL1RN, CD14, and tissue factor, failed to have benefit, suggesting that these genes are only a small part of a polygenic disease; blocking only this small part would have little overall effect." (PMID 35275946, 2022). "Besides, the relative composition of CXCR2+ N00 and CD274+IL1RN+ N02 was also increased in immunosuppressive sepsis BALF, indicating that the N00 and N02 neutrophil subpopulations might be more crucial to sepsis‐induced immunosuppression than other subpopulations." (PMID 39887584, 2025). "Notably, N02 characterized by IL1RN and CD274 was unique to BALF and absent in peripheral blood, suggesting a distinct population in the lung environment of sepsis patients." (PMID 39887584, 2025).
breast carcinoma (10 papers, 2006 to 2025). "Among postmenopausal AA women, IL1RN-rs4251961 was inversely associated with breast cancer risk, with CT/CC genotypes associated with a decreased risk (OR=0.65, 95% CI, 0.42-1.01)." (PMID 23991131, 2013). "Carriage of the mutant alleles of IL1RN was independently associated with shortened disease free and overall survival rates in Caucasian patients with breast cancer." (PMID 19267917, 2009). "Moreover, genetic polymorphisms of IL1RN are found to be associated with individual susceptibility for breast cancer development in Korean women." (PMID 32977823, 2020). "Interestingly, mutant alleles of IL1RN were associated with shortened disease-free and overall survival among Caucasian women with breast cancer." (PMID 23704896, 2013). "In the present study, the IL1RN long/2 gene polymorphism was independently associated with an unfavourable prognosis in breast cancer patients, while presence of the mutant alleles of IL1A -889 and IL1B +3953 were only associated with a shortened overall survival in a univariate analysis." (PMID 19267917, 2009). "The IL1RN gene polymorphism might be of prognostic value as carriage of the two mutant alleles was independently associated with shortened disease free and overall survival in Caucasian patients with breast cancer." (PMID 19267917, 2009). "Concerning the clinical studies, gene expression was analyzed in normal and tumor tissues across breast cancer subtypes and results indicated that IL1RN expression was higher in the tumor compared to the adjacent normal tissue." (PMID 39201290, 2024). "IL1RN was positively correlated with macrophage infiltration in breast cancer Her2 and Luminal A patients." (PMID 39201290, 2024). "We studied the influence of four common gene polymorphisms (IL1A -889C/T, IL1B -511C/T, IL1B +3953E1/E2, and IL1RN long/2) of the IL-1 family on survival in 262 Caucasian patients with breast cancer by univariate and multivariate survival analysis." (PMID 19267917, 2009). "The aim of this study was to evaluate any role of specific SNPs in the interleukin genes IL1A, IL1B, IL1RN, IL4R, IL6 and IL10 in predisposition to breast cancer susceptibility and severity." (PMID 16842617, 2006). "Combined with our results, it was speculated that CCL22, FOXJ1, and IL1RN may play an important role in ameliorating the prognosis of breast cancer patients through involving in immune response." (PMID 32977823, 2020). "The aim of this study was to evaluate polymorphisms in specific cytokine genes [IL1A +4845G>T, IL1B -511C>T, IL1B +3954C>T, IL1RN +2018T>C, IL4R -1902A>G, IL6-174G>C and IL10-1082G>A] in a case control model to determine any associations with breast cancer susceptibility, severity and survival." (PMID 16842617, 2006). "Biomarkers including FOXJ1, CCL22, ABCA3 and IL1RN may be good prognostic factors in breast cancer." (PMID 36397112, 2022). "There are no prior reports of the IL1RN +2018 polymorphism in breast cancer." (PMID 16842617, 2006). "The results from our study do not support the hypothesis that the cytokine polymorphisms studied [IL1A +4845G>T, IL1B -511C>T, IL1B +3954C>T, IL1RN +2018T>C, IL4R -1902A>G, IL6-174G>C and IL10-1082G>A] are associated with breast cancer susceptibility and severity." (PMID 16842617, 2006). "Neutrophil infiltration had a direct relationship with the expression of IL1R1, IL1RN, IL1RAP, IL6ST, CXCL3, CXCL5, and CXCL6 in most of the subtypes of the breast cancer patients analyzed." (PMID 39201290, 2024). "The relationship between ESR1 gene expression with IL1R1 or IL1RN genes has not been described for breast cancer." (PMID 39201290, 2024). "Gene expression associated with ER status in breast cancer patients was analyzed and results indicated that IL1R1 and IL1RN gene expression levels were non-significant among patients, whereas those with high IL6ST expression levels had a positive ER status." (PMID 39201290, 2024).
breast carcinoma (continued). "ABCA3, CCL22, FOXJ1, IL1RN, and MAP2K6 may serve as good prognostic factors, while KCNIP3 and MRPL13 may be poor prognostic factors for the prognosis of breast cancer." (PMID 32977823, 2020). "Examples of diseases that can reliably be diagnosed through salivary analysis are pancreatic (miR-3679-5p and miR-940), lung (cytokines IL1RN, IL1B, CXCL10), and breast cancers (phenylalanine, tryptophan), as well as myocardial infarction (C-reactive protein, myoglobin, and myeloperoxidase)." (PMID 32019170, 2020). "In conclusion, ABCA3, CCL22, FOXJ1, MAP2K6, and IL1RN may serve as good prognostic factors, while KCNIP3 and MRPL13 may be poor prognostic biomarkers to predict the recurrence and prognosis of breast cancer." (PMID 32977823, 2020). "In addition to an upregulation of transcription factors, we found an increased expression of IL1RN and the matrix metalloproteinases MMP2 and MMP3 in PRAME overexpressing breast cancer cells." (PMID 30602372, 2019). "Moreover, we performed immunohistochemical staining in breast cancer patient samples using antibodies directed against TGFA, IL1RN and PI3K." (PMID 23704896, 2013). "Polymorphisms within key interleukin genes (IL1A, IL1B, IL1RN, IL4R, IL6 and IL10 do not appear to play a significant overall role in breast cancer susceptibility or severity." (PMID 16842617, 2006). "Additionally, many markers we observed that defined our monocyte clusters (FABP5, FN1, IL1RN, CCL3, CCL4, CXCL8, CXCL3, IL1B) during transient, short-term CM stimulation, were elevated in either PD-L1pos or PD-L1neg TAMs isolated and sequenced from breast cancer." (PMID 40176808, 2025). "However, IL1RN, IL6ST, CXCL3, CXCL5, and CXCL6 gene expression levels were non-significant concerning clinical survival of breast cancer patients according to the Cox proportional Hazard model." (PMID 39201290, 2024). "However, IL1RN, IL6ST, CXCL3, CXCL5, and CXCL6 gene expression levels were non-significant concerning clinical survival of breast cancer patients." (PMID 39201290, 2024).
psoriasis (10 papers, 2013 to 2025). An autoimmune condition characterized by red, well-delineated plaques with silvery scales that are usually on the extensor surfaces and scalp. "The anti-inflammatory genetic mediators associated with psoriasis are IL1RN, IL4, IL10, IL13, and IL19." (PMID 37569685, 2023). "In human inflammatory skin diseases IL-1RN gene polymorphisms are discussed in association with allergic contact dermatitis and psoriasis." (PMID 36518750, 2022). "In this meta‐analysis, we systematically reviewed case–control studies on the association between psoriasis risk and genetic variants in the IL1‐RN and IL‐10 genes." (PMID 30523673, 2019). "It has been shown that innate IL1RN gene mutations are associated with the development of psoriasis, and animal studies have also found that knocking out the IL1RN gene can contribute to the development of psoriasis." (PMID 40540498, 2025). "Our study also found that new genes like CSF2RB, IL1RN, CCL5, MMP9, CD53, NCF2 and TLR2 associated with Inflammation present high expression both in psoriasis and atherosclerosis." (PMID 34122426, 2021). "The present study carried out a meta‐analysis to investigate whether the interleukin‐1 receptor antagonist (IL‐1RN) VNTR polymorphism and three IL‐10 single‐nucleotide polymorphisms (SNPs) rs1800896, rs3021097, and rs1800872 are associated with psoriasis risk." (PMID 30523673, 2019). "In addition, rs610604 (TNFAIP3) and rs17728338 (TNIP1), but not rs2066808 (IL23R) and rs397211 (IL1RN), were associated with psoriasis in a case-control study." (PMID 24069534, 2013).
rheumatoid arthritis (10 papers, 2014 to 2025). A chronic, systemic autoimmune disorder characterized by inflammation in the synovial membranes and articular surfaces. "In a mouse model of rheumatoid arthritis, loss of IL1RN leads to stronger and more persistent inflammation." (PMID 40979590, 2025). "It was shown that IL1RN has beneficial effects in treating rheumatoid arthritis where the pro-inflammatory cytokine TNFα is a driver for the pathological progression." (PMID 32244522, 2020). "A pharmaceutically engineered analogon of IL1RN has become a treatment option for advanced rheumatoid arthritis and other chronic inflammatory diseases." (PMID 25114677, 2014). "Ex vivo administration of a retroviral vector carrying IL1RN cDNA to human autologous synovial fibroblasts, followed by their intra-articular injections into the metacarpophalangeal joints, lead to a lower swelling and pain in patients with rheumatoid arthritis." (PMID 36986717, 2023). "Collectively, our data suggest that possible sustained IL-1 signaling by the deletion of Il1rn elicited a skeletal site-dependent response in the bone marrow composition of the long bone and jaw, and this can represent an additional link between rheumatoid arthritis and periodontal pathology." (PMID 32471111, 2020).
type 2 diabetes mellitus (10 papers, 2012 to 2025). A type of diabetes mellitus that is characterized by insulin resistance or desensitization and increased blood glucose levels. "Our findings are strongly supported by previous reports that IL-1α-889 C/T polymorphism and IL-1 receptor antagonist allele (IL1RN*2) were associated with nephropathy in diabetes mellitus." (PMID 32733443, 2020). "Notably, IL1rn is involved in granulocyte adhesion and is associated with PN in diabetes db/db murine models, and Saa3 is an inflammatory marker of Schwann cell injury in peripheral nerves." (PMID 36922895, 2023). "The IL1RN gene has been found to have variable numbers of an 86 base pair (bp) tandem repeat in intron 2, and this polymorphism is associated with various inflammatory diseases (systemic lupus erythematosus, type 2 diabetes mellitus (T2DM)) and ischemic stroke." (PMID 37421595, 2023). "We previously showed that hypomethylation of the IL1RN and NFKB1 gene promoters is associated with dysregulation of the IL-1β/IL-1Ra axis in type 2 diabetes." (PMID 40821781, 2025).
asthma (9 papers, 2008 to 2026). "In a UK cohort, maternal smoking during pregnancy in infants with the rs2234678 GG SNP of IL1RN was also identified as a gene-environment interaction that increased the susceptibility to repeated asthma and persistent asthma in children." (PMID 36292755, 2022). "Genotypic/haplotype analyses of the tag SNPs in IL1RN and asthma susceptibility for the NYUBAR population as a whole resulted in findings that were in accordance with previous publications using different analyses and independent cohorts." (PMID 32204425, 2020). "We discovered a gene–environment interaction (GEI) of IL1RN polymorphisms with childhood environmental tobacco smoke (ETS) exposure on asthma susceptibility in an urban adult population." (PMID 32204425, 2020). "When stratified by childhood ETS exposure, those with childhood ETS and the rare homozygous genotype of IL1RN had a higher risk for early onset asthma compared to those with common genotypes in multivariate analysis." (PMID 32204425, 2020). "Analysis of GEI indicated that childhood ETS exposure disrupted the protective effect of some haplotypes/genotypes of IL1RN for asthma and turned them into high-risk polymorphisms for early onset asthma." (PMID 32204425, 2020). "Our previous publications have shown that maternal smoking during pregnancy interacts with the IL13 and IL1RN genes and increases the risk of asthma and wheezing." (PMID 24004509, 2013). "Region 2p12-q22.1 contains the DPP10 gene that has previously been identified as an asthma and total IgE susceptibility gene and the IL1RN gene identified using asthma as the primary phenotype." (PMID 18442398, 2008). "Thus these results from nonstratified analyses using our admixed cohort supported the previously reported finding in the German population that several candidate IL1RN SNPs and haplotypes have association with asthma susceptibility." (PMID 32204425, 2020). "Moreover, childhood ETS exposure led to significant elevation of risk for early onset asthma for the subpopulation who carried rare genotypes of the tag SNPs of IL1RN including the GG genotype in SNP rs2234678." (PMID 32204425, 2020). "Indeed, among the children with childhood ETS exposure (N = 230), carriers of the IL1RN rare homozygous genotypes had a significantly higher risk of developing early onset asthma compared to the carriers of other more common genotypes." (PMID 32204425, 2020). "Thus, in the group without childhood ETS exposure, our data indicated that GG in SNP rs2234678 and rare genotypes in other tag SNPs of IL1RN were associated with significantly reduced risk (p < 0.05) of asthma susceptibility (or protective effect) relative to the common genotypes." (PMID 32204425, 2020). "We selected a cut point of age 10 as early onset asthma to be comparable with previous studies of IL1RN." (PMID 32204425, 2020). "When stratified by genotypes of IL1RN and focused on subjects with rare homozygous genotypes of IL1RN, we found that childhood ETS exposure elevated the risk for early onset asthma." (PMID 32204425, 2020). "Logistic regressions were used to study the GEI between IL1RN variants and childhood ETS exposures on asthma and early onset asthma, respectively, adjusting for population admixture and other covariates." (PMID 32204425, 2020). "More importantly, 11 mRNAs were overlapped in our sequencing data, MalaCards database and asthma-associated genes, including IL4, IL-10, MMP9, VCAM-1, Il1rl1, Alox5, Il1rn, Ccr3, Cysltr1, Epx, and Ccl24." (PMID 31231429, 2019). "The differential association of childhood ETS exposure with early onset asthma within various IL1RN genotype groups has not been reported in the literature." (PMID 32204425, 2020). "Our data, therefore, suggest that childhood ETS exposure modifies the IL1RN haplotype/genotype-dependent risk for asthma susceptibility and bridge a knowledge gap and explain previous discordant study results on GEI between variants of IL1RN and ETS exposure in asthma studies." (PMID 32204425, 2020).